MYC (MYC proto-oncogene, bHLH transcription factor)
Diseases named in the same sentence as MYC in open-access papers (continued):
Sharing a sentence is not in itself a finding about the gene and the disease.
cancer (continued). "Current models posit that MYC is essential for KRAS-driven cancer; RAS activation stabilizes MYC; in turn, MYC renders cells vulnerable to DNA damage and apoptosis." (PMID 28152508, 2017). "This work was focused on c‐MYC, but a similar approach can be applied to other pathways for PDAC as well as for other cancer types." (PMID 28275007, 2017). "Accordingly, it was concluded from this study that MYC inhibition would be a promising therapeutic strategy for a significant fraction of SCLC, an aggressive cancer with extremely high mortality rate." (PMID 27105536, 2016). "Among analysis, MYC, Argonaute2 (AGO2), Y-box binding protein 1 (YBX1), cyclin E1 (CCNE1) were involved in organismal abnormalities and cancer." (PMID 27463019, 2016). "Taken together with our study, TFAP4 appears to be initially upregulated by MYC or MYCN, after which it cooperatively regulates the same target genes to maximize rapid transcriptional activity in cancer cells." (PMID 27448979, 2016). "In this review, we summarized the critical roles of MYC and HIF-1 in adjusting cancer metabolism to the ambient oxygen level and discussed the proven and putative roles of the NDRG family in regulating cancer metabolic reprogramming." (PMID 27447861, 2016). "For example, the lncRNA JPX, the TFs MYC and E2F1 and the miRNA let-7 play crucial roles in human cancers." (PMID 27322142, 2016). "TBP expression also correlates with the expression of MYC, RAS and checkpoint kinases in a number of cancers." (PMID 27725641, 2016). "JQ1 is known to induce growth suppression by transcriptional inhibition of numerous genes, including MYC, MYCN and ASCL1, in human cancer cells." (PMID 27764802, 2016). "Using our non-B DNA search algorithm, we systematically inspected the c-MYC and BCL-2 genes that are often involved in translocations in human cancers, for potential H-DNA- and Z-DNA-forming sequences." (PMID 27532010, 2016). "The 8q24 region of the human genome, which contains MYC and PVT1, is one of the most common sites of cancer-related amplifications." (PMID 27232880, 2016). "Of the canonical pathways, the regulators of metabolism were most affected whilst MYC and STAT4 were predicted upstream regulators to be activated, as was the pathway modulating the anti-cancer pharmaceutical agent Streptozocin." (PMID 26987907, 2016). "Among all cancers types, kidney renal clear cell carcinoma (KIRC) showed the strongest upregulation of PVT1 and increased levels of both MYC and PVT1 correlated with the clinical outcome." (PMID 27366943, 2016). "PVT1 lncRNA and MYC protein expressions are correlated in primary human tumors, and the copy number of PVT1 was increased in more than 98% of cancers that also showed an increase of MYC copies." (PMID 26602695, 2016). "Given the reports of the roles of NDRGs in the MYC and HIF signaling pathways, we here suggest a possible connection between NDRG and cancer metabolism, and predict the potential of NDRG for application in the ongoing battle against cancer." (PMID 27447861, 2016). "Furthermore, our data suggests that the uncontrolled growth of cancer cells under nutrient deficient conditions is, at least in part, underpinned by the ability of oncogenic signaling pathways such as AKT/mTORC1/S6K1 and/or oncogenes such as MYC, to maintain elevated ribosome biogenesis." (PMID 27385002, 2016). "Ribosome footprinting and polysome profiling experiments have detected more than 250 genes, including MYC, MDM2, CDK6, and AFR6 that are affected by silvestrol treatment making it a promising drug to treat cancer." (PMID 28083147, 2016). "These miRNAs also affect other targets such as MYC, cyclin D and HMG2A, indicating the importance of such miRNAs in controlling several pathways related to cancer." (PMID 27540517, 2016).
cancer (continued). "Meanwhile MYC also transcribes MTDH expression and stimulates oncogenetic activity in cancer cells including MM." (PMID 26683226, 2016). "The cancer samples of patients with late-onset tumors presented higher YWHAE and MYC expression and lower CDC25B expression in relation to to early-onset GC samples (p<0.05 for all analyses)." (PMID 27863420, 2016). "Based on these findings, we investigated the relationship between MYCN or MYC and SGO1/SGO2 expression levels using The Cancer Genome Atlas (TCGA) pan-cancer gene expression datasets." (PMID 27539729, 2016). "A previous study proposed that activated forms of the MYC and MYCN oncoproteins promote miR-9 expression via gene amplification in human cancers." (PMID 27612152, 2016). "Our findings uncover BPTF as a crucial c-MYC co-factor required for its biological activity and suggest that the BPTF-c-MYC axis is a potential therapeutic target in cancer." (PMID 26729287, 2016). "Regions of high level gain or amplification encompassed key cancer genes such as MYCN (2p), the EVI1/MDS1 cluster (3q), FGFR1 (8p), OCT4 and MYC (8q) and KRAS (12p) of which a number are potential therapeutic targets." (PMID 26334103, 2015). "Reduced PTEN function cooperates with MYC and HER2 activation in conferring aggressive phenotype to cancer cells." (PMID 26672755, 2015). "MYC proto-oncogenes (MYC, MYCN, MYCL) are transcription factors that play key roles in both normal development and cancer." (PMID 25294817, 2015). "In T-LBL, aberrant expression of MYC generally occurs downstream of activated NOTCH signaling, which is the major contributor to the pathogenesis of T-lymphoblastic malignancies." (PMID 26416427, 2015). "In total, FISH results on both PTEN deletions and amplifications of HER2, CCND1 and MYC were available in subsets of 1,047 (HER2), 792 (MYC) and 1,149 (CCND1) cancers." (PMID 26672755, 2015). "As we have seen in other cancers and cancer cell lines, knockdown of DCLK1 reduced the expression of stem cell pluripotency factors MYC, NANOG, POU5F1/OCT4, and SOX2 in Caki-2 cells." (PMID 25605241, 2015). "Some target genes are involved in oncogenesis, such as c-MYC and cyclin D1 regulating cancer proliferation, MMP-7 regulating cancer invasion." (PMID 25658088, 2015). "One possible explanation for the selective presence of DIS3 somatic mutations in haematological cancers is the prominent role exerted by MYC, and to a lesser extent by RAS, in these cancers." (PMID 25925570, 2015). "Similar to other cancers, recurrent amplification of 7p11.2, 8q24.21, and 11q13.2, harboring EGFR, MYC, and CCND1, has previously been reported in ESCC." (PMID 26465158, 2015). "These potential alternative driver alterations were found to affect known cancer genes, including amplification of PIK3CA or MYC, and likely driver genes mapping to the 8p11-p12 amplicon, including ZNF703, RAB11FIP1, LSM1, PPAPDC1B, WHSC1L1 and FGFR1." (PMID 25994018, 2015). "Particularly, there were 88 DEGs (hypergeometric P = 0.0019) that overlap with the known cancer genes, including PDAC related genes such as MYC, BRCA1, and KRAS, which indicates that the DEGs of this study have close bond with the cancer progression indeed." (PMID 26425543, 2015). "A previous study of mucinous gastric carcinoma showed that c-MYC amplification, defined as a c-MYC:CEP8 ratio > 2.0, was strongly correlated with the advanced stages of cancer." (PMID 26426996, 2015).
cancer (continued). "Our data provide new information on a subtype of cancer samples enriched for gene sets related to ERG-fusion, ESC and MYC + indicating poor prognosis on an early stage of PCa development (low Gleason score)." (PMID 25115192, 2014). "A recent study identified a positive feedback loop consisting of MYC, the nicotinamide-phosphoribosyltransferase (NAMPT) enzyme, the SIRT1 inhibitor deleted in breast cancer 1 (DBC1) and SIRT1." (PMID 24884974, 2014). "The let-7 miRNA family, which was the first reported group of TSmiRNAs in cancer, represses a number of oncogenic proteins such as KRAS, high mobility group AT-hook 2 (HMGA2), and v-myc myelocytomatosis viral oncogene homolog (MYC)." (PMID 24551595, 2014). "In particular, we find significant evidence that the AP1/MYC TF pair has an important role in regulating gene expression in MET related to BC, PC, and to cancer in general." (PMID 24612742, 2014). "Multiple studies have demonstrated a positive correlation between MYC and SIRT1 expression in various human cancers, including hepatocellular carcinoma and colorectal cancer." (PMID 25085992, 2014). "This gene is an ubiquitin protein ligase and facilitates the proteasomal degradation of target proteins involved in cancer such as CCNE (e.g. cyclin-E) and MYC (e.g c-MYC)." (PMID 24782526, 2014). "In various cancer cell lines, when MEK is inhibited by U0126, there is a marked reduction in MYC protein expression levels with concomitant growth suppression." (PMID 25017515, 2014). "The MYC/MAX/MAD network is a key axis in the cell decision-making for differentiation and proliferation, and it is altered in several types of cancer." (PMID 24349289, 2013). "Physiological upregulation of TOP1MT has been observed in cellular stress responses encompassing the induction of mitochondrial biogenesis and in cancer cells, where TOP1MT is induced by the proto-oncogene MYC." (PMID 23982517, 2013). "We identify copy number gain of ATAD2 as a regulator of ATAD2 expression, present the first data linking ATAD2 overexpression to MYC activation, and provide functional data suggesting ATAD2 as a therapeutic target in MYC-dependent cancers." (PMID 23393560, 2013). "It has been demonstrated that OCT4, SOX2, c-MYC, LIN28, NANOG and KLF4 are required for ESC self-renewal and pluripotency and are upregulated in some aggressive cancers and in CSCs." (PMID 24040120, 2013). "Our results demonstrated that 5 of the 6 up-regulated mRNAs in “HTLV-1 infection pathway” increased (ICAM1, WNT2B, MYC, HLA-F and TGF-β1) and 3 of the 5 down-regulated mRNAs in “Pathways in cancers” decreased (CDH1, PTENP1, HSP90AA1)." (PMID 24367666, 2013). "Taken together, SOX2 and the other SOX family members activate the expression of MYC and CCND1, perhaps bypassing the blocked ER-mediated mitogenesis by which cancer cell proliferation can be maintained." (PMID 24355041, 2013). "The fact that late-stage cancers frequently have multiple copies of RAS and MYC oncogenes strongly hints that their general incurability more than occasionally arises from high antioxidant levels." (PMID 23303309, 2013). "In this study, we exploited the predominant expression of LysM in myeloid cells to generate c-Mycfl/fl LysMcre/+ mice, which lack c-Myc in macrophages, to investigate the role of macrophage c-MYC expression in cancer." (PMID 23028984, 2012).
cancer (continued). "Genes such as MYC and PIK3CA, known to be activated in many cancers tend to show more micro-amplifications; others known to be inactivated in cancer such as RB1 and PTEN display comparatively more micro-deletions." (PMID 23284754, 2012). "We show that many translocation-prone pairs of regions genome-wide, including the cancer translocation partners BCR-ABL and MYC-IGH, display elevated Hi-C contact frequencies in normal human cells." (PMID 23028501, 2012). "Rearranged genes showed to be highly connected to well-known altered genes in cancer such as AR, RB1, MYC, and BRCA1." (PMID 22811706, 2012). "Most of these regions have been validated to encompass or closely near to cancer related genes such as MDM2, MYC, EGFR, ERBB2, CCND1, ARNT." (PMID 23285074, 2012). "It is worthy to note that c-MYC target genes that are perturbed by PTEN expression involve the regulation of cell growth, cell metabolism, and protein synthesis, suggesting that the c-MYC-regulated target genes may potentially play important roles in the development of PTEN-deficient cancers." (PMID 22347425, 2012). "Among all cancer-related genes on chromosome 8, DLC1 and MYC play a major role in hepatocarcinogenesis, and evidence for their involvement in the development of HCC is presented next." (PMID 22580498, 2012). "The typical hESC-specific TFs like OCT4 and c-Myc (also known as MYC), appeared to be important in control of the undifferentiated state of cancer cells." (PMID 22041030, 2011). "Notch1 signaling is increased in a variety of cancers and activates downstream target genes, including HES1, HES5, DTX1, NRARP, and c-MYC." (PMID 20161710, 2010). "The finding of an enrichment in embryonic TFs related to MYC and TCF-3, which are indeed regulators of cancer stem cell pathways, reinforces the TIC identity of the PSs." (PMID 20500816, 2010). "It was reported that the c-MYC protein up-regulates PEG10 expression and that there is a positive correlation between increased c-MYC and PEG10 expression in various cancers." (PMID 20084274, 2010). "Another gene, the NMYC and STAT interactor (NMI), which interacts with NMYC, MYC, MAX, FOS, other transcription factors and BRCA1, is overexpressed in human leukaemias and other cancers." (PMID 19240718, 2009). "For the first time, we are able to identify in cancer microarray data significant indirect effects of transcription factors, such as PPAR proteins, E2F1 and MYC, on survival." (PMID 18358079, 2008). "The MYC gene family members, c-MYC, MYCN and MYCL, are involved in the biology of many cancer types." (PMID 18851746, 2008). "The ecMYC E1 locus exhibited enhancer hallmarks exclusively in MYC-amplified G3-MB but not in other MYC-dependent cancer cell lines, including those with MYC amplification." (PMID 42018144, 2026).
cancer (continued). "MAX, a core component of the MYC/MAX/MAD network, forms heterodimers with MYC or MAD proteins to regulate genes involved in cell proliferation, differentiation, and metabolic reprogramming, particularly in cancer and inflammatory diseases." (PMID 41614919, 2026). "Interestingly, chronic Cr (VI) exposure can induce cancer stem cell-like properties and cell transformation by significantly increasing EZH2 and MYC expression levels." (PMID 41362669, 2026). "The antagonistic BASP1 effect on MYC and the MYC dependency on TNIK could enhance the development of strategies to interfere with oncogenic functions of the cancer driver MYC." (PMID 41785318, 2026). "MYC stabilization is not a well-established aspect of MYC regulation, making it a topic of ongoing research in cancer biology." (PMID 39779613, 2025). "BET protein inhibitors can inhibit the expression or activity of MYC and MYCN in cancer cells." (PMID 40076599, 2025). "Finally, to evaluate the clinical relevance of c-MYC methylation by SMYD3, we assessed c-MYC K158/K163Me levels by immunohistochemistry in normal and cancer tissues from CRC patients with advanced-stage cancer." (PMID 40588481, 2025). "Interestingly, MYC also interacts with integrin αV (ITGAV), another critical player in different types of cancer." (PMID 40076599, 2025). "Furthermore, FTO can stabilize mRNA transcripts of MYC and CCAAT enhancer binding protein alpha (CEBPA), increasing the proliferation and survival of cancer cells." (PMID 40483535, 2025). "These include Akt, MYC, and MAPK, which are commonly hyperactivated in cancers." (PMID 41146310, 2025). "This may be explained by an increase in MYC gene copy number in the HAP1 cell line, which is a common occurrence in cancer cells." (PMID 40596037, 2025). "We show that CPSF1 amplification frequently, but not always, co-occurs with MYC amplification in patients and cancer cell lines." (PMID 41463412, 2025). "Additionally, the top hub genes identified in the PPI network of FZD4 miRNA targets, including MYC, EGFR, MDM2, and CDK1, were also involved in many aspects of cancer progression." (PMID 40667070, 2025). "Although an attractive target, developing drugs to inhibit MYC has historically been challenging due to the absence of a readily identifiable crevice for high-affinity binding of low molecular weight anti-cancer compounds." (PMID 39875774, 2025). "While, generally, tRNA anticodon pools were found to be stable across human tissues, alterations in tRNA expression were observed across cancer types, mediated via activation of oncogenic pathways such as PI3K/AKT/mTOR, and MYC, which regulate RNA polymerase III-mediated tRNA expression." (PMID 41190243, 2025). "In addition to the transcriptional downregulation of MYC, CBL0137 is known to exert anti-cancer activity by inhibiting the NF-kβ pathway and via trapping of SSRP1 into chromatin." (PMID 39706891, 2025). "Core nodes include IL6, MYC, VEGFA, EGFR, and ESR1, all of which play essential roles in cancer development and may act as critical molecular regulatory hubs." (PMID 40045358, 2025). "This underscores the importance of finding new non-canonical interactors of MYC to better understand MYC-regulated transcription, which will give us a better understanding of how to target MYC-driven cancers." (PMID 41415380, 2025). "Several critical cancer-related pathways, including mitogen-activated protein kinase/extracellular signal-regulated kinase (MAPK/ERK), WNT, transforming growth factor ß (TGFß) and sonic hedgehog (SHH), have MYC as a key downstream target." (PMID 40365336, 2025). "Therefore, we treated cancer cells with inhibitors of actomyosin and adhesion molecules, and then analyzed ATF5 localization, EGR1 expression, JAK phosphorylation, and MYC expression." (PMID 40124511, 2025).